USP20 (ubiquitin specific peptidase 20)
Diseases named in the same sentence as USP20 in open-access papers (continued):
Sharing a sentence is not in itself a finding about the gene and the disease.
metabolic disease (5 papers, 2022 to 2024). A congenital disorder (due to inherited enzyme abnormality) or acquired (due to failure of a metabolically important organ) disorder resulting from an abnormal metabolic process. "To prove the concept that knockdown of Usp20 can treat metabolic disease, we used LNP-encapsulated siRNA to silence hepatic Usp20 in mice and analyzed the metabolic profile." (PMID 39173829, 2024). "This study suggests that the RNAi-based therapy targeting hepatic Usp20 has a translational potential to treat metabolic disease." (PMID 39173829, 2024). "Subsequently, it was also found that long-term high-sugar and high-fat diet induced increased phosphorylation of USP20, stabilized HMGCR protein and increased cholesterol, which caused metabolic diseases." (PMID 35754818, 2022). "To test whether knocking down Usp20 can treat metabolic diseases, we fed mice a HFD." (PMID 39173829, 2024).
head and neck tumour (1 paper, 2025). "These in vivo results further suggest that USP20 plays a key role in promoting head and neck tumour progression by stabilizing CTSL." (PMID 41261048, 2025).
USP20 also shares sentences with these, for which no sentence is quoted: hyperlipidemia (2 papers); acute myeloid leukemia (1); adult T cell leukemia (1); autoimmune disease (1); bladder urothelial carcinoma (1); cardiovascular diseases (1); colorectal adenocarcinoma (1); diabetes (1); diabetic foot ulcers (1); head and neck squamous cell carcinoma (1); hypertrophy (1); infection (1); lung carcinoma (1); osteosarcoma (1); thymoma (1); uterine corpus endometrioid carcinoma (1).